GNAS (GNAS complex locus)
Diseases named in the same sentence as GNAS in open-access papers (continued):
Sharing a sentence is not in itself a finding about the gene and the disease.
tumor (continued). "Furthermore, NGS for tumor protein 53, SMAD4, mammalian target rapamycin, and CTNNB1 genes are useful in identifying advanced neoplasia when combined with GNAS/MAPK mutation with a sensitivity and specificity of 88% and 98%, respectively." (PMID 38731128, 2024). "First, we determined GNAS mutational status in tumor samples in the entire cohort of patients." (PMID 36497102, 2022). "German longhaired pointers carrying GNAS mutations in the tumor may be used as a disease model for the development and testing of novel therapies to kill the tumor with somatic mutations in the GNAS gene." (PMID 36151521, 2022). "GNAS mutation might be associated with an increased proliferation rate according to semiquantitative evaluation of the number of mitotic figures in the neoplasms." (PMID 36151521, 2022). "In the tumour stage, GNAS gene mutation was recorded highest in the late stage at 67.9% (95% CI: 0.497–0.843) than the early stage, while in tumour location, the colon has the highest GNAS gene mutation of 50.5% (95% CI: 0.332–0.676) for the tumour located in the colon." (PMID 36428574, 2022). "Interesting questions have arisen from these RNA sequencing studies, i.e., what is the impact of potential USP8 or GNAS driver mutations on tumor transcriptome profiles, and how does the expression of distinct PitNET cell lineage transcription factors affect other tumor lineage types." (PMID 33808624, 2021). "However, in GNAS mutated tumours, DNA hypomethylation and limited chromosomal alterations have been noted." (PMID 33805450, 2021). "GNAS mutations p.R201C and p.R201H were detected in three tumours (10%)." (PMID 33737597, 2021). "Transcriptional profiling of such a large cohort of a single molecular type of cancer allows for a thorough understanding of the tumor’s genomic landscape, including the identification of genes affected by mutations (GNAS, MYCN, PPM1D, and PRKAR1A), and fusion transcripts (ZBTB20 and NCOR1)." (PMID 33741928, 2021). "However, GNAS mutations have been more extensively studied in tumors of the pancreatic and biliary system than in GC." (PMID 33933102, 2021). "Germline mutations occur in several known genes (AIP, PRKAR1A, GPR101, GNAS, MEN1, CDKN1B, SDHx, MAX) as well as familial cases with currently unknown genes, while somatic mutations in GNAS are present in up to 40% of tumours." (PMID 33805450, 2021). "Since COX2 has a known protumorigenic role in colon neoplasia, oncogenic mutations in GNAS may therefore activate a proinflammatory response, which favors tumor development." (PMID 32532044, 2020). "The mechanism of tumor progression and mucin hypersecretion remains largely unknown, but GNAS mutation is a promising contributor." (PMID 32700107, 2020). "GNAS mutations were detected in 40 of 61 (66%) IPMNs, and the following mutations were observed in codon 201: R201C in 22 tumors, R201H in 17 tumors, and R201Y in 1 tumor." (PMID 32934653, 2020). "In colorectal cancer (CRC), GNAS mutations are found very infrequently (2.5%), and, when present, the tumor shows peculiar clinical and pathological features resembling PMP of appendiceal origin, i.e., mucinous histology, right side origin, peritoneal metastases and association with KRAS mutations." (PMID 33266161, 2020). "To investigate the tumorigenesis effect of GNAS in vivo, we subcutaneously injected wild type (WT) or GNAS-knockout (GNAS-cas9) HepG2 cells into nude mice and found that GNAS knockout caused less tumor formation and significantly decreased tumor size compared with the WT group." (PMID 32123532, 2020). "Tumors with GNAS mutation, tumors with gain of the GNAS region and tumors with no alteration (GNAS wt and no gain) were comparable in terms of sex, age at surgery, grade, secretion and tumor size." (PMID 33168091, 2020). "Interestingly, GNAS has also been shown to harbor tumor-suppressor gene abilities in other tumors, suggesting that the output of GNAS mutations is highly contextual in cancers." (PMID 32887490, 2020).
tumor (continued). "The mutated GNAS allele found in one tumor was also biallelically transcribed." (PMID 28160572, 2017). "4.2% of all tumor sequences deposited today show activating mutations in GNAS." (PMID 28683819, 2017). "Only one tumor with low expression of StAR harbored the GNAS mutation R201H." (PMID 27606678, 2016). "This agreement indicates that KRAS mutations at codon 12 or GNAS mutations at codon 201 could play a key role as the driver of carcinogenesis, providing a selective advantage in tumor formation associated with these IPMNs." (PMID 27095449, 2016). "Tumor molecular and clinical characteristics according to GNAS mutation status." (PMID 24498230, 2014). "Activating GNAS hot-spot mutations have been detected in many other tumor types." (PMID 25291362, 2014). "GNAS mutation may be related to the initiation of tumor genesis and represent indolent villous/papillary growth pattern of tumors in various organs." (PMID 24312577, 2013). "However, recent studies have revealed that some of these lesions, even without cytological dysplasia, may harbor somatic mutations associated with neoplasia, particularly in the GNAS and KRAS genes." (PMID 40964650, 2026). "Tumor cell proliferation in PIT1 might be associated with GNAS copy number gain." (PMID 37958702, 2023). "Group 1 included GNAS wild-type (GNASwt) DG tumors (except for one GNASwt, SG tumor), group 2 included mainly DG tumors with a high proportion of samples with GNAS mutation, and group 3 included basically SG tumors with a low percentage of GNAS-mutated (GNASmut) ones." (PMID 36497102, 2022). "Thus, GNAS mutations represent a unique driver mutation for this benign tumor type." (PMID 30736805, 2019). "The GNAS p.(Arg844Cys) mutation, as well as variants of uncertain significance AKAP13 p.(His641Pro) and EPAS1 p.(Ser478del) were detected in the tumor." (PMID 40175770, 2025). "An exploratory analysis of 89 patients with mPCNs was performed to assess the incidence of advanced neoplasia arising during follow-up after the initial EUS-FNA, according to GNAS mutation status." (PMID 40622417, 2025). "Treatment of HRAS-mutant tumours with tipifarnib over long periods resulted in resistant tumours that harbour a mutation in NF1 and GNAS." (PMID 40332222, 2025). "We validated the presence of WIDs in two independent genes (HLA-B and GNAS) in patient-derived tumor samples through PCR amplification of a region spanning the deleted introns, followed by Sanger sequencing." (PMID 40348775, 2025). "To evaluate the role of MEG3 in mediating the effects of the GNAS mutation on tumor invasion, we examined the effects of MEG3 knockdown in GH3 cells expressing mutant GNAS." (PMID 38827318, 2024). "Although the detailed mechanisms of BRAF and APC loss and GNAS expression in this study are not fully understood, shifts in these important signaling pathways involved in tumorigenesis may contribute to changes in the tumor environment and could be associated with the ICI response." (PMID 39796090, 2024). "Intriguingly, MEG3 expression further increased in the 16 GHPA tumor tissues with mutant GNAS compared with the 28 wild-type tumors (p = 0.006)." (PMID 38827318, 2024). "Our study revealed significant dynamic changes in BRAF, APC, and GNAS mutations during ICI treatment, shedding light on the tumor’s molecular evolution under therapeutic pressure." (PMID 39796090, 2024). "A recent study using blood and tumour samples from PMP patients (samples used from Clinical Trials.gov; ID: NCT02073500), identified GNAS mutations (R201H and R201C) and suggested the resulting Gsα to be a potential neoantigen." (PMID 36723696, 2023).
tumor (continued). "The report detected that tumours with USP8 and GNAS mutations have distinct transcriptomic profiles compared to tumours without these tumour driver variants, indicating that transcriptomic studies can bring valuable information on PitNET functional aspects." (PMID 36774501, 2023). "We then transplanted MC1R-depleted B16F10-dCas9 cells expressing wild-type GNAS or the R201C mutant into mice and monitored tumor growth over time." (PMID 37714844, 2023). "In the presence of anti-PD-1 treatment, the effect of the GNAS R201C mutant in promoting MAP tumor growth was even more pronounced." (PMID 37714844, 2023). "Similar to observations made from B16F10 and MAP tumors, expression of the GNAS R201C mutant in 4T1-HA repressed Cxcl9/10/11 expression and promoted tumor growth in comparison to expression of wild-type GNAS." (PMID 37714844, 2023). "RNF43 is a tumor suppressor gene, and loss-of-function mutations in RNF43 often accompany GNAS mutations during IPMN development." (PMID 37470859, 2023). "To identify the prevalence of the GNAS p.A204D somatic mutation among dogs suffering from FCC, we genotyped 49 tumor samples from 34 affected dogs using Sanger sequencing." (PMID 36151521, 2022). "TOP DNA panel identified KRAS (G12D), GNAS (R201C), and FBXW7 (R367*) variants in the primary tumor." (PMID 35255903, 2022). "Here, patients with iCCA carrying the GNAS rs7121 genotype TT displayed fewer apoptotic tumor cells and reduced OS compared to those with patients carrying the GNAS rs7121 genotype CT and CC (OR = 2.74, 95% CI = 1.03–7.28 p = 0.025)." (PMID 36497451, 2022). "The upregulation of the ORC family, RFC family, and PCNA in patients with GNAS copy number gain likely led to the elevated DNA biosynthesis and the enhanced tumor cell proliferation." (PMID 36307579, 2022). "Besides the GNAS c.393C>T polymorphism, somatic missense mutations such as R201H, R201L, R201s, and R201C in the exon 8 of the GNAS gene and mutations in the exon 9 such as Q227R and Q227L were identified to have a clinical significance in several tumor entities." (PMID 36297195, 2022). "Ding’s study in HCC cell lines also demonstrated that GNAS played a tumor-promoting role in inflammation-related HCC progression." (PMID 35052777, 2022). "Consistent with common activation of GNAS in tumors, we observed a frequent amplification of this gene (in 45.4% of all tumor cell lines), whereas it had a deletion of one copy in only 0.8% of the cell lines." (PMID 36461044, 2022). "Mutant GNAS, as an onco-modulator of Kras-induced neoplasia, causes phosphorylated YAP to be sequestered in the cytoplasm and alters tumor progression." (PMID 33408779, 2021). "MC1R also interacts with the signal transducer GNAS, recently suggested to be tumor-promoting in RCC." (PMID 34067022, 2021). "Survival correlated with tumour grade, and detection of IDH1, IDH2 and GNAS mutations in plasma pre‐ and postoperatively." (PMID 34528398, 2021). "In pancreatic carcinogenesis, salt inducible kinases (SIK) were recently identified as critical tumor suppressors inhibited by GNAS signaling." (PMID 34201897, 2021). "We characterized the GNAS locus in two independent somatotroph tumor cohorts: one of 23 tumors previously published (PMID: 31883967) and classified by pan-genomic analysis, and a second with 82 tumors." (PMID 34299200, 2021). "PMP is a rare neoplastic disease, deriving in most cases from a mucinous appendiceal tumor from LAMN, HAMN or adenocarcinoma, all associated with co-KRAS and GNAS mutations." (PMID 34930348, 2021).
tumor (continued). "Activating MAPK pathway mutations including KRAS c.35G>A (p.G12D; COSM521) and GNAS c.601C>T (p.R201C; COSM27887) were identified in two tumor samples (2/15, 13%), with these mutations co-occurring in both tumors (NECC015, NECC012)." (PMID 32544169, 2020). "Patients with somatic mosaicism for codon 201 GNAS develop McCune-Albright syndrome, characterized by somato- or somatomammotroph hyperplasia or tumor, polyostotic fibrous dysplasia, cafe-au-lait spots, and precocious puberty." (PMID 32201880, 2020). "Our findings for the first time suggest a tumor-promoting role of GNAS in inflammation-related HCC progression and provide a novel potential target for HCC therapy." (PMID 32123532, 2020). "Our findings for the first time suggest a tumor-promoting role of GNAS in inflammation-related HCC progression and afford a novel potential target for HCC therapy." (PMID 32123532, 2020). "Our findings for the first time indicate a tumor-promoting role of GNAS in inflammation-related HCC progression and provide a novel potential target for HCC therapy." (PMID 32123532, 2020). "The high mutation rate of GNAS in PMP patients has been observed about 10 years ago, when fresh tumor tissue or formalin-fixed, paraffin-embedded tissue was used for variant detection." (PMID 32700107, 2020). "GNAS mRNA and protein expression levels were higher in tumor tissues, compared with those in the corresponding para-tumor normal tissues." (PMID 32123532, 2020). "The GNAS (OMIM-139320, NM_000516.6) (p.R201H, c.602G > A) pathogenic variant in addition to the PDE4DIP p.S977I missense variant was observed in the tumor sample from patient #3." (PMID 32098292, 2020). "Blood-NGS identified less RAS/GNAS mutations compared to tissue-NGS (4.2% vs. 60.9%, P < 0.0001) and showed poor concordance with tissue for well-/moderately differentiated tumours." (PMID 32733093, 2020). "The mutations identified in APC, GNAS, and BRAF were found in serous (1/64, 1.6%), endometrioid (1/5, 20.0%), and mucinous (1/1, 100.0%) tumor samples, respectively." (PMID 31197119, 2019). "In particular, SIKKO rescues both organoid growth in vitro and subcutaneous tumor growth following GNAS R201C silencing, and these findings have been confirmed in human pancreatic ductal adenocarcinomas (PDA)." (PMID 30723708, 2019). "A small proportion of initial tumours had SNVs in the G-protein gene, GNAS (5%; 2/38), IDH1/2 (5%; 2/38), and the Rb-specific cell-cycle regulation genes CDK6 and RB1 (5%; 2/38)." (PMID 32082376, 2019). "The analysis of GNAS in neoplasias of the gastrointestinal tract is shedding new light on the significance of the mutation." (PMID 29544460, 2018). "We replication tested our prognostic markers in 296 tumours from the Australian cohort (appendix pp 8, 37–38), in which all prognostic markers identified in QUASAR 2 (except GNAS mutations) had been assessed." (PMID 30042065, 2018). "Tumor cell content of pseudomyxoma peritonei FFPE samples estimated from HE stainings, and variant allele frequencies (VAF) of KRAS and GNAS from targeted sequencing." (PMID 28426742, 2017). "The expression of GNAS correlated significantly with tumor grade, being more prevalent in well- and moderately differentiated GCs." (PMID 28683819, 2017). "However, prognosis also depends on the tumor grade and underlying molecular alterations, such as mutations in KRAS, BRAF, and GNAS." (PMID 40746921, 2025). "A study conducted by Tang and colleagues demonstrated the tumor-suppressive role of MEG3 lncRNA, showing that mutations in the α subunit of the stimulatory G protein (GNAS) upregulate MEG3 lncRNA expression and are associated with less invasive growth hormone-secreting PitNETs." (PMID 41141357, 2025).
tumor (continued). "The higher prevalence of NEJGNAS detection compared to NEJRPL22 may stem from the higher transcript expression level of GNAS in tumours, enhancing its immunogenicity and tumour-specific killing by TCRG4.1." (PMID 39972144, 2025). "Beyond its diagnostic role, GNAS has not been firmly linked to advanced neoplasia, and its long-term prognostic value remains unexplored." (PMID 40622417, 2025). "Similarified GNAS upregulation by LPS stimulation enhances IL-6 expression by elevating m6A methylation of mRNA, while GNAS knockdown diminishes IL-6, thereby inhibiting tumor growth." (PMID 40034695, 2025). "Moreover, in patients with GNAS copy number gain, upregulation of cell cycle and DNA replication pathways was observed, which suggested stronger tumor cell proliferations in these patients." (PMID 39513543, 2025). "Because GNAS mutations are speculated to participate in upregulating MEG3 expression, the expression levels of MEG3 in NFPA and GHPA tumor tissues were quantified via RT-qPCR." (PMID 38827318, 2024). "The two cases lacking GNAS mutation were reevaluated, and despite a tumor content adequate for analysis, no mutations were found." (PMID 38791144, 2024). "It has been shown that GNAS has activating mutations in most of the KIRC, and overexpression of this gene in KIRC may act as a promoter of tumor cells through a PKA-dependent pathway." (PMID 38180750, 2024). "This dual observation underscores the importance of interpreting GNAS mutations within the broader context of tumor dynamics and patient-specific factors, rather than viewing them solely as markers of progression." (PMID 39796090, 2024). "Conversely, KRAS (p = 2.67e−90), FBXW7 (p = 1.29e−14), BRAF (p = 9.32e−8), GNAS (p = 2.54e−29), and SMAD2 (p = 3.93e−5) mutated tumors were significantly more common in MSLN high expressing tumor samples versus MSLN low expressing tumor samples." (PMID 39174744, 2024). "Consequently, this study aimed to elucidate the effect of GNAS mutations on the GHPA phenotype, especially on tumor invasion, and the mechanism involved." (PMID 38827318, 2024). "Our observations of GNAS mutations in both responders and non-responders suggest a context-dependent role that highlights the complexity of tumor-immune interactions under ICI therapy." (PMID 39796090, 2024). "Frequently, mutations in the KRAS gene occur concomitantly with mutations in the GNAS gene in the RAP1 signaling pathway, which involves numerous biological processes, including invasiveness, adhesion, cell migration and polarization, and tumor metastasis." (PMID 37509254, 2023). "Genome sequencing of 12 somatotroph PitNET have also found mutations in GNAS, but no other recurrent somatic variants, and in this report authors demonstrated average 129 somatic variants per tumor genome (range 11–273) and 2.3 variants per exome." (PMID 36026497, 2022). "However, all of the three pathogenic variants, KRAS (G12D), GNAS (R201C), and FBXW7 (R367*) remained positive in the recurrent tumor with VAFs ranging from 1.9 to 4.3%." (PMID 35255903, 2022).